TRAV39 (T cell receptor alpha variable 39)
Description:
V region of the variable domain of T cell receptor (TR) alpha chain that participates in the antigen recognition. Alpha-beta T cell receptors are antigen specific receptors which are essential to the immune response and are present on the cell surface of T lymphocytes. Recognize peptide-major histocompatibility (MH) (pMH) complexes that are displayed by antigen presenting cells (APC), a prerequisite for efficient T cell adaptive immunity against pathogens. Binding of alpha-beta TR to pMH complex initiates TR-CD3 clustering on the cell surface and intracellular activation of LCK that phosphorylates the ITAM motifs of CD3G, CD3D, CD3E and CD247 enabling the recruitment of ZAP70. In turn ZAP70 phosphorylates LAT, which recruits numerous signaling molecules to form the LAT signalosome. The LAT signalosome propagates signal branching to three major signaling pathways, the calcium, the mitogen-activated protein kinase (MAPK) kinase and the nuclear factor NF-kappa-B (NF-kB) pathways, leading to the mobilization of transcription factors that are critical for gene expression and essential for T cell growth and differentiation. The T cell repertoire is generated in the thymus, by V-(D)-J rearrangement. This repertoire is then shaped by intrathymic selection events to generate a peripheral T cell pool of self-MH restricted, non-autoaggressive T cells. Post-thymic interaction of alpha-beta TR with the pMH complexes shapes TR structural and functional avidity.
Synonyms: TCRAV27S1; TCRAV39S1
Gene: T-cell receptor variable (V) gene on chromosome 14 (22,304,054 to 22,304,553, forward strand). Ensembl gene ENSG00000211818.
Subcellular location: Cell membrane
Gene Ontology:
Biological process: response to bacterium
Cellular component: plasma membrane
Homologues: Orthologues: macaque TRAV39 (93% identical), mouse Trav23 (58% identical). Paralogues in human: TRAV20 (49% identical), TRAV21 (45% identical), TRAV17 (45% identical), TRAV10 (44% identical), TRAV36DV7 (44% identical), TRAV6 (44% identical), TRAV24 (43% identical), TRAV5 (43% identical), TRAV7 (43% identical), TRAV27 (40% identical), TRAV13-1 (38% identical), TRAV25 (38% identical), and 11 more.
Diseases named in the same sentence as TRAV39 in open-access papers:
TRAV39 is named in the same sentence as 2 diseases in open-access papers, as found by Europe PMC text mining. Sharing a sentence is not in itself a finding about the gene and the disease. The quoted sentences say what the papers report.
esophageal squamous cell carcinoma (2 papers, 2022 to 2023). Esophageal squamous cell carcinoma (ESCC) is a type of esophageal carcinoma (EC) that can affect any part of the esophagus, but is usually located in the upper or middle third. "For example, one recent study revealed that TRAV39 expression was associated with memory CD4 T cell activation in Esophageal Squamous Cell Carcinoma." (PMID 36987861, 2023).
TRAV39 also shares sentences with these, for which no sentence is quoted: Tumor (1 paper).